INS (insulin)
Diseases named in the same sentence as INS in open-access papers (continued):
Sharing a sentence is not in itself a finding about the gene and the disease.
Hepatic steatosis (continued). "Bacterial DNA deposited within metabolic tissues activates the cGAS/STING pathway promoting inflammation, which impairs insulin production and lowers insulin secretion from pancreatic islets in addition to promoting hepatic steatosis, inflammation, and fibrosis." (PMID 39235984, 2025). "Astragalus Polysaccharides (APS), an active metabolite of Astragalus membranaceus Bunge has been shown to be effective in attenuating metabolic disorders induced by HFD, including decreasing the extent of hepatic steatosis, inhibiting body mass gain, and improving insulin resistance." (PMID 40552158, 2025). "Hepatic steatosis, although infrequent, could contribute to altered glucose and lipid metabolism, amplifying systemic inflammation and insulin resistance." (PMID 41156159, 2025). "Consecutive, the hepatic steatosis and insulin signal transduction worsen." (PMID 40565181, 2025). "In an insulin-resistant state, impaired suppression of hormone-sensitive lipase triggers excessive lipolysis and elevates levels of FFAs, which are re-esterified in the liver into TGs, contributing to hepatic steatosis." (PMID 40869401, 2025). "Some studies suggest benefits for insulin sensitivity and liver steatosis." (PMID 40244398, 2025). "Previous theories were based on the “two-hit hypothesis”, which suggested that the first “hit” involves hepatic steatosis, or the accumulation of fat in the liver, due to increased levels of free fatty acids and insulin resistance." (PMID 41011683, 2025). "These diets deliver a greater improvement in fat oxidation and insulin sensitivity that might explain the significant decrease in the hepatic steatosis and central adiposity which are crucial aspects for MASLD/T2DM management." (PMID 39860434, 2025). "Furthermore, curcumin enhances lipid buffering capacity, and decreased inflammatory adipokine secretion results in lower hepatic steatosis and improved peripheral tissue insulin sensitivity." (PMID 41471280, 2025). "Furthermore, inflammatory cytokines (e.g., TNF-α and IL-6) impair insulin signaling, leading to insulin resistance, which stimulates liver fat synthesis and inhibits fat degradation, exacerbating liver steatosis." (PMID 40746546, 2025). "Some researchers have hypothesized that increased resistance to insulin may contribute to the development of fatty liver." (PMID 41282546, 2025). "Chronic systemic inflammation, characteristic of IBD, may contribute to hepatic lipid accumulation through inflammatory cytokines such as tumor necrosis factor-alpha and interleukin-6, which interfere with insulin signaling and promote hepatic steatosis." (PMID 41416325, 2025). "The present results demonstrate that FFDZ exerts anti-NAFLD effects by enhancing glucose tolerance and insulin sensitivity, as well as regulating the Ampk signaling pathway to ameliorate lipid metabolism disorder, lipotoxicity, hepatic steatosis, and inflammatory responses." (PMID 40144651, 2025). "The generally accepted “two hit hypothesis” enunciates that hepatic steatosis (first hit) and insulin resistance (second hit) in conjunction modulated an increasing cell oxidative stress promoting the progression of MASH and collagen deposition (fibrosis)." (PMID 40643509, 2025). "The twin cycle hypothesis supported that energy restriction, such as LFD, would reduce hepatic steatosis, normalize the liver’s insulin sensitivity, and liver glucose production." (PMID 41374037, 2025). "Hepatokines, that are proteins secreted by hepatocytes, have been linked to insulin resistance in non-hepatic tissues during the progression of hepatic steatosis." (PMID 40760121, 2025). "Insulin and ANGPTL4 are key, opposing regulators of LPL activity, insulin enhances LPL, whereas ANGPTL4 inhibits it, and LPL activity is closely linked to circulating free fatty acid levels and the development of hepatic steatosis." (PMID 41226996, 2025).
Hepatic steatosis (continued). "Samuel and Shulman’s foundational work illustrates how hepatic steatosis impairs insulin signaling pathways by potentially decoupling peripheral glucose and lipid metabolism, which are components captured by the TyG index, from their downstream vascular consequences." (PMID 41180199, 2025). "Similarly, glycemic indicators such as insulin and C-peptide were also associated with human gut microbiome composition, together with derived predictors of insulin sensitivity and hepatic steatosis." (PMID 41228466, 2025). "We examined the abnormal changes in physiological and biochemical indicators, including body weight, hepatic steatosis, insulin sensitivity, glucose metabolism, serum lipid profile, inflammatory response, and antioxidant defense function, which are key indicators of NAFLD development." (PMID 40144651, 2025). "Liver-specific deletion of CerS6 prevents insulin resistance and hepatic steatosis." (PMID 40057751, 2025). "In contrast, global MST4 deficiency has no impact on systemic insulin sensitivity or liver steatosis in obese mice." (PMID 40024534, 2025). "Menaquinone-4 (MK-4) and menaquinone-7 (MK-7), the bioactive forms of vitamin K2, have been shown to modulate insulin signaling, suppress hepatic lipogenesis, and reduce inflammation, thereby contributing to improved lipid profiles and reduced hepatic steatosis." (PMID 40870774, 2025). "Paradoxically, liver-specific HuR-deficient mice display enhanced insulin sensitivity and lower blood glucose levels compared to wild-type controls following 24 weeks of high-fat diet (HFD) feeding, despite exhibiting more pronounced hepatic steatosis." (PMID 40809813, 2025). "reuteri GL-104 decreased fasting blood glucose and lipid profiles, and improved glucose tolerance in genetic diabetic-obese (db/db) mice with a mutation in the leptin receptor Additionally, L. reuteri GMNL-263 improved insulin responses and ameliorated hepatic steatosis in high fructose-fed rats." (PMID 39520540, 2025). "Accordingly, reducing the intake of foods with added sugar consumption may help improve hepatic steatosis and metabolic parameters such as insulin sensitivity and liver enzyme levels in obese adolescents diagnosed with NAFLD." (PMID 40362809, 2025). "Additionally, estrogens have been shown to exert hepatoprotective effects by modulating lipid metabolism, reducing hepatic steatosis, and improving insulin sensitivity." (PMID 40217790, 2025). "Additionally, EF-2001 improved glucose metabolism, increasing glucose tolerance by 20% and insulin sensitivity by 15%, while reducing fat buildup in the liver by 24%, indicating protection against fatty liver disease." (PMID 40722433, 2025). "In addition, high-intensity exercise has been associated with favorable DNA methylation changes in metabolic regulatory genes, contributing to improved insulin sensitivity and attenuated fatty liver disease." (PMID 40682843, 2025). "Furthermore, treatment with GIP/ICG@P/R8 NPs effectively improves systemic metabolic profiles, including a 9.23% reduction in body weight after 14 days, enhanced insulin sensitivity, and amelioration of fatty liver." (PMID 41256211, 2025). "Moreover, calorie restriction induces autophagy in liver cells, promoting hepatic insulin sensitivity and mitigating fatty liver disease, a prevalent consequence of T2D." (PMID 40216734, 2025). "Some pieces of evidence have shown that improvements in systemic glucose homeostasis and insulin sensitivity account for the rapid effect of MSB on the remission of hepatic steatosis, but investigations of lipid alterations in the early postoperative recovery phase are still lacking." (PMID 38632600, 2024). "Additionally, we identified the impact of KA in DIO mice, showing that KA reduced levels of lipids in the blood, inhibited lipid accumulation in the liver and white adipose tissue (WAT), enhanced insulin sensitivity, and reduced hepatic steatosis." (PMID 38655315, 2024).
Hepatic steatosis (continued). "Butanoic acid impacts the i) increase of leptin release and insulin sensitivity, ii) decrease of hypercholesterolemia and hepatic steatosis, iii) decrease of HOMA-IR index and iv) modulation of cellular events that regulate the assembly and delivery of lipoproteins." (PMID 38904913, 2024). "Improving hepatic steatosis and triglycerides indeed improves insulin sensitivity in the liver." (PMID 39056667, 2024). "In particular, hepatic steatosis can impair insulin action in the liver." (PMID 39703225, 2024). "Notably, the findings demonstrated that, even in the absence of weight loss, adherence to the Mediterranean diet led to a reduction in hepatic steatosis and an improvement in insulin sensitivity." (PMID 39229589, 2024). "Additionally, knocking out KHK in mice protects against hepatic steatosis and improves insulin sensitivity." (PMID 38971308, 2024). "To assess whether a given co-expression network module was related to clinical traits, we correlated the MEs to ALT, AST, GGT, HDL, LDL, total cholesterol, fasting glucose, insulin, hepatic steatosis, plasma TG, BMI z-scores, and DNL." (PMID 38668319, 2024). "Therefore, food with a high glycemic index increases de novo lipogenesis, hypertriglyceridemia, insulin, and hepatic steatosis." (PMID 38673981, 2024). "Furthermore, curcumin lowered triglyceride and cholesterol deposition in the liver, preventing hepatic steatosis and improving hepatic insulin sensitivity." (PMID 39056667, 2024). "In humans, the hepatic expression of GlP-1R has also been questioned, even though earlier studies have reported its presence in human hepatocytes, and suggested that GLP1R decreased hepatic steatosis by modulating the insulin signaling pathway or activating lipid oxidation." (PMID 39607493, 2024). "This study showed that GPS is effective in improving the phenotype of HFHC-induced NASH mice, including reducing body weight gain and liver weight, decreasing serum levels of ALT, TG, TC, and LDL-C, and improving insulin sensitivity, as well as attenuating hepatic steatosis." (PMID 38515850, 2024). "Indeed, male mice drinking 30% fructose solution on the Boston chow diet for ten weeks gain weight, develop hepatic steatosis, and have impaired hepatic insulin signaling." (PMID 39796558, 2024). "In this context, the hepatic steatosis and insulin signal transduction worsen." (PMID 38891828, 2024). "The liver is the main organ responsible for glucose and lipid metabolism; it has been seen that patients with liver steatosis have elevated levels of free fatty acids (FFAs) due to a failure to suppress lipolysis mediated by insulin, allowing the release of excess FFAs into the bloodstream." (PMID 38611675, 2024). "Moreover, a crossover randomized controlled trial sought to assess the impact of distinct dietary patterns on insulin sensitivity within the context of hepatic steatosis." (PMID 39229589, 2024). "In support of this theory, studies using hepatocytes isolated from both healthy and steatotic mice have shown that liver steatosis impairs hepatokine secretion, which can subsequently disrupt lipid metabolism, induce inflammation, and lead to insulin resistance in other tissues." (PMID 39409124, 2024). "This highlights a key role for CEACAM1-dependent insulin clearance pathways in maintaining insulin sensitivity and limiting hepatic steatosis by promoting hepatic insulin clearance and mediating the anti-lipogenic effect of acutely released insulin in hepatocytes." (PMID 39640841, 2024). "Moreover, we expanded our adjustments to include additional covariates like insulin, AST, hepatic steatosis, and GGT, which are all recognized risk factors for GDM." (PMID 38414896, 2024). "Moreover, under these conditions, P2Y13-R–KO mice exhibited diminished hepatic insulin sensitivity and more severe liver steatosis than their control counterparts." (PMID 38470490, 2024).
Hepatic steatosis (continued). "Notably, butanoate/butyrate production can be enhanced after bariatric surgery 69, while favorable effects of butyrate have been proved on MASLD, including attenuating hepatic steatosis and inflammation while enhancing insulin sensitivity." (PMID 39247824, 2024). "Our results showed that high-dose SZ-A treatment could significantly reduce the body weight, decrease the serum lipids, improve insulin tolerance, and ameliorate liver steatosis and fibrosis in MAFLD model mice." (PMID 39458927, 2024). "Adiponectin, known for its anti-diabetic and insulin-sensitizing properties, directly reduces hepatic steatosis and inflammation and may also reduce hepatic stellate cell activation and migration." (PMID 39409124, 2024). "Insulin resistance further exacerbates hepatic steatosis, as insulin’s ability to suppress adipose tissue lipolysis diminishes while simultaneously activating de novo lipogenesis pathways through transcription factors like SREBP-1c and carbohydrate-responsive element binding protein (ChREBP)." (PMID 38673981, 2024). "Additional mechanisms that contribute to the reduction in hepatic steatosis include suppression of caloric intake, inhibition of de novo lipogenesis in the liver, and increased insulin sensitivity in adipose and muscle tissue, which promotes glucose uptake in peripheral organs." (PMID 39409124, 2024). "The variability in findings may imply that increased resistin levels are correlated more significantly with heightened tissue resistance to insulin, thereby elevating the likelihood of hepatic steatosis." (PMID 38732626, 2024). "Serum triglyceride and glucose levels may be especially useful in the diagnosis of liver steatosis due to the importance of insulin resistance and increased serum levels of triglycerides in the pathophysiology of lipid accumulation in the liver tissue." (PMID 38611675, 2024). "In addition, fetuin-A mRNA expression is elevated in individuals with NASH/MASH compared to those with simple fatty liver, where it negatively regulates adiponectin, thereby impairing its insulin-sensitizing and anti-inflammatory effects." (PMID 39409124, 2024). "Acetate and propionate not only impact glucose production in the liver, potentially improving glucose homeostasis and insulin sensitivity, but also regulate lipid metabolism in the liver by reducing fatty acid and cholesterol synthesis, thus mitigating hepatic steatosis." (PMID 38539862, 2024). "A “two-hit hypothesis” suggests that insulin resistance acts as a “first hit” to result in hepatic steatosis, and oxidative injury acts as a “second hit” involved in the development of NAFLD in OSA." (PMID 36694611, 2023). "Whole-body deletion of FGFR4 improves insulin sensitivity, glucose metabolism, and liver steatosis." (PMID 36586437, 2023). "Interestingly, Nlrp3−/− mice fed HFD are more insulin and glucose sensitive, and protected from hepatic steatosis, compared with Nlrp3 sufficient controls." (PMID 36994095, 2023). "A previous narrative review reported that improvement in hepatic steatosis and liver function following HIIT was associated with improved liver mitochondrial function, increased hepatic PPAR-α, and PPAR-γ content, improved insulin sensitivity, and suppression of hepatic de novo lipogenesis." (PMID 36937342, 2023). "Currently, several plant-derived flavonoids have been also shown to exert anti-diabetic effects and were able to attenuate hyperlipidemia and hepatic steatosis either directly by suppressing de novo lipogenesis or indirectly through increasing insulin sensitivity and adipose tissue lipogenesis." (PMID 36986192, 2023). "Remarkably, the present work shows that MaR1 is able to reverse the decrease in ADIPOQ expression induced by HFD in DIO mice and by TNF-α in both models of cultured human adipocytes, which potentially contribute to a parallel improvement on insulin sensitivity or alleviation of hepatic steatosis." (PMID 37371501, 2023).
Hepatic steatosis (continued). "Patients with NAFLD develop hyperinsulinemia as a result of impaired whole-body insulin clearance, which may further drive hepatic steatosis." (PMID 37200978, 2023). "Furthermore, non-invasive hepatic steatosis indices are positively correlated with fasting blood insulin, C peptide, triglyceride, total cholesterol, and LDL-C levels, but negatively correlated with HDL-C levels, which are also associated with atherosclerosis." (PMID 37056670, 2023). "Furthermore, it also stimulates the secretion of GLP-1 and inhibits macrophage-mediated inflammation and lipid accumulation, which can lead to improved insulin sensitivity and reduced hepatic steatosis." (PMID 37570840, 2023). "Furthermore, because hepatic steatosis is associated with IR, we evaluated the effect of CARF-OE on glucose tolerance through serum insulin tolerance and glucose tolerance tests after 14 weeks of feeding on an HFD." (PMID 37048142, 2023). "Furthermore, chronic HFD consumption in Japanese macaque mothers was shown to increase hepatic steatosis in the liver of adult offspring, a relationship that was regulated by increased insulin signalling." (PMID 38201940, 2023). "Similarly, higher values of plasma FFAs during the clamp characterize the greater IR in T2DM with fatty liver and hepatic steatosis correlated with basal and insulin-stimulated plasma FFAs." (PMID 36980862, 2023). "It was reported that ChREBP could have a beneficial role on insulin sensitivity independently of hepatic steatosis." (PMID 36923222, 2023). "Through its multifaceted impact, PPEs significantly alleviated NAFLD liver steatosis, primarily by augmenting lipolysis and thermogenesis, encouraging thermogenesis, including insulin secretion, alleviating insulin resistance and modulating related signaling pathways." (PMID 37960226, 2023). "Our results demonstrated that supplementing gnetin C to the HFCD diet can effectively protect mice from developing NAFLD pathology by reducing liver weight, BW, and blood glucose levels, improving insulin sensitivity, and inhibiting liver steatosis and fibrosis." (PMID 37764672, 2023). "Furthermore, RDX8940 improves hepatic steatosis and insulin sensitivity in insulin-resistant mouse models, which has the potential to treat NASH and NAFLD." (PMID 37570840, 2023). "Some of the modifications include improvement in insulin sensitivity and glucose tolerance, decrease in body weight, decrease in hepatic steatosis, white adipose tissue (WAT) beigeing, and an increase in WAT eosinophils and M2 macrophages with increased expression of M2 markers (Ym1 and Arg1)." (PMID 38044996, 2023). "However, IL-17A blockade led to significantly improved whole-body insulin sensitivity, and it reduced hepatic steatosis and LD diameter to levels comparable with CD11cWT littermates." (PMID 37140993, 2023). "Furthermore, administration of the USP1-specific inhibitor ML323 to mice fed an HFD effectively reduced fat mass, improved hepatic steatosis, and improved insulin sensitivity." (PMID 38012162, 2023). "Reduction of glucose-6-phosphatase activity and increase in adiponectin receptors, adiponectin, and AMPK phosphorylation have been associated with a decrease in fasting glucose, HbA1c, TG, cholesterol, and hepatic steatosis and increased insulin sensitivity and glucose tolerance." (PMID 36771347, 2023). "After adjusting for confounding variables, including pre-pregnancy BMI, age, hepatic steatosis, AST, GGT, ALT, FPG, adiponectin, and insulin, the results revealed a positive association between RC (per 5 mg/dL) and GDM in pregnant women (OR = 1.473, 95% CI 1.200–1.809, p < 0.001)." (PMID 37544989, 2023). "In essence, our findings corroborate the significant mitigation effect of PPE intervention on NAFLD-related liver steatosis, mainly by promoting lipolysis and thermogenesis, enhancing insulin secretion, alleviating insulin resistance and regulating related signaling pathways." (PMID 37960226, 2023).